RAD51 (RAD51 recombinase)
Diseases named in the same sentence as RAD51 in open-access papers (continued):
Sharing a sentence is not in itself a finding about the gene and the disease.
breast tumors (33 papers, 2006 to 2024). "In this study, we investigated the cellular effects of a heterozygous somatic tumor variant, RAD51 G151D, we identified in 1 out 32 breast tumors analyzed by DNA sequencing." (PMID 27513445, 2016). "Here we describe a set of mutations associated with human breast tumors that occur in a common structural motif of RAD51." (PMID 25539919, 2015). "In addition, a subset of the patients had decreased RAD51 protein expression on their breast tumors as we hypothesized that loss of protein expression might be a sign of underlying inactivating germline mutations." (PMID 25918678, 2015). "Importantly, up-regulation of Rad51 was a common feature of BRCA1-deficient breast tumors." (PMID 20205718, 2010). "The gene expression investigations revealed the substantial down-regulation of BRCA1 (P = 0.02), CHEK2 (P = < 0.0001), BRIP1 (P = < 0.0001), and RAD51 (P = 0.01) in breast tumors compared with adjacent normal tissues." (PMID 35715772, 2022). "Our previous studies showed that VPA, at a safe therapeutic dose of 0.5 mM, sensitizes breast tumor MCF7 cells and the primary cultured breast tumor cells to IR by impeding HR function with Rad51 inhibition." (PMID 33842359, 2021). "A pilot study assessed the feasibility to measure the formation of BRCA1, FANCD2 and RAD51 foci after IR in small pieces of breast tumors ex vivo." (PMID 33670893, 2021). "Overall, 26% (15/57) of the breast tumor samples showed a low RAD51 score 24 h after anthracycline-based chemotherapy." (PMID 33670893, 2021). "This new approach is innovative because it now allows assessment of RAD51 foci in FFPE breast tumor samples directly." (PMID 33003546, 2020). "In establishing a connection between patient breast tumor samples and RAD51 formation, breast tumor samples were irradiated and subjected to RAD51 ionizing radiation induced foci (IRIF) analysis." (PMID 30934991, 2019). "Analysis of TCGA data revealed elevated RAD51 expression in breast tumors compared to normal breast tissues, especially in TNBC subtype." (PMID 31492187, 2019). "To examine the clinical feasibility of the RAD51 assay, we scored archival breast tumor samples, including PALB2‐related hereditary cancers." (PMID 30377213, 2018). "In this study, we developed a new computational method to infer the level of cell proliferation in breast tumor samples by referring to gene expression profiles generated by RNAi-mediated knockdown of BRCA1 or RAD51 in MCF-10A cells." (PMID 27788678, 2016). "In breast tumors, expression analysis of RAD51/TODRA, E2F1 and TPIP shows perturbed regulation of RAD51 expression, and the associated increase in RAD51 expression correlates with an aggressive tumor phenotype." (PMID 26230935, 2015). "RAD51 is involved in HR, and quantification of nuclear RAD51 foci has also been used to evaluate HR in various cell systems including primary breast tumors." (PMID 24843000, 2014). "Interestingly, RAD51 is overexpressed in primary breast tumors (n = 1097) compared to normal tissues (n = 114)." (PMID 31492187, 2019). "Notably, the assessment of DSB repair by measuring RAD51 foci in breast tumor samples has been proposed as predictor of chemo-sensitivity." (PMID 30283497, 2018). "B02, another RAD51 inhibitor, in combination with cisplatin significantly inhibited MDA-MB-231 breast tumor growth in mouse xenografts." (PMID 37798649, 2023). "In breast tumor initiating cells, increased EZH2 expands cell population through repressing RAD51 expression, and knockdown of EZH2 reduces the repression of RAD51 transcription by decreasing H3K27 trimethylation." (PMID 27494834, 2016). "Unfortunately, it is difficult to find reports in the available literature, which would directly bind RAD51 and XRCC2 SNP in DNA repair gene by HR with clinical-pathological features of breast tumour." (PMID 25743260, 2015).
breast tumors (continued). "Conversely, the expression of RAD51, as well as BRCA1, is reduced in almost one third of breast tumor cell lines and primary sporadic breast cancer cells." (PMID 25539919, 2015). "Previously, we have shown that low RECQL breast tumors were significantly associated with low PARP1, BRCA1 negative, low RAD51, low ATM, low nuclear pChk1, low nuclear Chk2, low XRCC1, low FEN1, low SMUG1, and low DNA-PKcs expression." (PMID 38134458, 2023). "Since our data about miR-182-5p expression indicate its remarkable up expression in breast tumors, especially in TNBC and its potential effects on downregulating CHEK2 and RAD51 in TNBC, we examined the level of cell-free miR-182-5p in the blood plasma samples from the patients." (PMID 35715772, 2022). "The RAD51/GMN co-IF on FFPE specimens has previously been described for breast tumor specimens, but optimal test parameters (γH2AX threshold, RAD51 foci cut-off and HRD threshold) were not extensively defined and not available for EC and OC." (PMID 34203855, 2021). "We also examined the RAD51-TODRA pathway in vivo, in breast tumors." (PMID 26230935, 2015). "RAD51 expression in breast tumors was positively correlated with E2F1 expression and negatively correlated with TODRA, indicating that E2F1 indeed regulates the bidirectional promoter in vivo in the malignant state, in the same manner we observed in cell lines." (PMID 26230935, 2015).
melanoma (32 papers, 2010 to 2025). A malignant, usually aggressive tumor composed of atypical, neoplastic melanocytes. "The increased expression of RAD51 is connected to aggressiveness and metastatic potential of several cancers including melanoma cells which is associated with reduced patient survival." (PMID 32719412, 2020). "Here we confirm the specific effect of RAD51 overexpression on overall survival of melanoma patients and analyzed the underlying mechanism." (PMID 32719412, 2020). "In keeping with previous studies, PTEN-deficient HT144 and UACC62 melanoma cells were also RAD51-deficient." (PMID 24830350, 2014). "We have confirmed the regulation of four exemplary genes, namely RAD51, BRCA1, BRCA2, and XRCC2 by vemurafenib treatment in further BRAF-mutated melanoma cell lines using RT-qPCR analysis at the mRNA level and the regulation of Rad51 at protein level using immunoblot analysis." (PMID 32719412, 2020). "Meanwhile, CDKN2A, CXCR4 and RAD51 were significantly up-regulated in melanoma compared with normal skin except CDKN1A (significantly down-regulated)." (PMID 38070141, 2023). "Consistent with this, we found that increasing concentrations of THZ531 decreased BRCA1 and Rad51 protein level, which correlates with a dose-dependent increase in DNA damage in both melanoma cell lines." (PMID 36309522, 2022). "RAD51 foci decreased in the melanoma cell cultures ARPA, RERO, ICNI and HV18MK and therefore these cell lines were defined as HR-deficient." (PMID 34073147, 2021). "Due to the finding of a high Rad51 level in melanoma cells, we have asked for its potential as a target protein in melanoma therapy." (PMID 32719412, 2020). "In contrast, we detected a reduction of RAD51 foci in the melanoma cell lines ICNI, RERO, ARPA, HV18MK, A375M, Mel624, and PMelL, which were defined as HR-deficient." (PMID 33297429, 2020). "Similar to the effect of Rad51 inhibition, the siRNA-mediated Rad51 knockdown sensitized the R and RR melanoma cells for MAPKi treatment." (PMID 32719412, 2020). "Additional inhibition of the MAPK pathway reduced reporter activity to 70% and Elk1 knockdown reduced it to 50%, confirming the role of Elk1 as one of the major transcription factors for RAD51 gene regulation in melanoma cells." (PMID 32719412, 2020). "Similar to the observations in melanoma cell lines, we show high Rad51 expression in metastatic melanoma tumor samples from 17 out of 25 patients by immunohistochemical staining." (PMID 32719412, 2020). "Rad51 inhibition enhances the effect of MAPKi treatment in R and RR melanoma cells in vivo and in vitro suggesting that Rad51 is a promising new therapeutic target for the treatment of MAPKi resistant melanoma." (PMID 32719412, 2020). "The viability analysis data show that inhibition of Rad51 strongly reduces the viability of all melanoma cells analysed, while the viability of other skin cells, including fibroblasts and keratinocytes, remained largely unaffected." (PMID 32719412, 2020). "We show that RAD51 and other homologous recombination repair genes are overexpressed in metastatic melanoma cell lines and in melanoma patient samples, which correlates with reduced survival of melanoma patients." (PMID 32719412, 2020). "For example, MS-275, which inhibits class I HDACs, including HDAC1, decreases RAD51 expression and blocks HR in melanoma cells." (PMID 30382096, 2018). "Instead of increasing levels of RAD51 on encountering cisplatin-induced interstrand crosslinks during replication, melanoma cells shut down RAD51 synthesis and instead boost levels of translesion synthesis DNA polymerase zeta to allow replication to proceed." (PMID 29254481, 2017).
melanoma (continued). "Ectopic expression of a tagged form of RAD51 and siRNA knockdown of translesion synthesis DNA polymerase zeta were used to investigate the mechanism that allowed cisplatin-treated melanoma cells to continue to replicate." (PMID 29254481, 2017). "We conclude that the reduction in RAD51 levels in A375 melanoma cells on cisplatin treatment is accompanied by a different DNA repair response to that seen in the non-melanoma cells." (PMID 29254481, 2017). "Specifically, Ku70, Ku86, and the DNAPK catalytic subunit were shown to be downregulated in melanoma cells, while Rad51 and DNAPK were downregulated in PCa cells upon HDAC inhibition." (PMID 20585447, 2010). "Furthermore, CDKN1A, CDKN2A, CXCR4 and RAD51 in the melanoma pathway, were also differentially expressed between normal skin and melanoma." (PMID 38070141, 2023). "Moreover, it was found that drug-resistant melanoma cells rely on RAD51 expression for survival and can be successfully targeted with Rad51 inhibitors." (PMID 33800547, 2021). "Our findings were consistent with the previous study that showed VPA could down-regulate both RNA and protein expression levels of RAD51 in human melanoma cells." (PMID 34576202, 2021). "For example, a recent study postulates a synthetic lethality of PTEN-deficient melanoma cells to Rad51 inhibition, as PTEN affects non-homologous end joining repair (NHEJ) as an alternative DNA double-strand break repair pathway to HRR43." (PMID 32719412, 2020). "Most strikingly, melanoma cells which developed resistance towards MAPK inhibitors could be efficiently targeted by Rad51 inhibitors similar to their sensitive counterparts, leading to DNA damage, G2/M arrest and apoptosis." (PMID 32719412, 2020). "We found that several HRR-associated genes, including DDB2, RAD51, BRCA1, XRCC2 and BRCA2, are overexpressed in melanoma cells compared to primary melanocyte cultures, while the expression of the NER-associated genes XPA, ERCC1 and ERCC4 showed no clear differences." (PMID 32719412, 2020). "In addition, Rad51 expression in melanoma cells was regulated on a transcriptional level by the MAPK signaling pathway with Elk1 as the main downstream transcriptional effector." (PMID 32719412, 2020). "The inhibition of Rad51 and the resulting blockade of the remaining HRR could be sufficient to induce death of melanoma cells and thus explain the high dependence of these cells on Rad51 expression." (PMID 32719412, 2020). "We could show that especially Elk1 is a critical downstream effector mediating increased expression of Rad51 in melanoma cells." (PMID 32719412, 2020). "Therefore, melanoma cells are sensitive to Rad51 inhibition, which results in an induction of apoptosis." (PMID 32719412, 2020). "In particular, RAD51 mRNA and protein expression is upregulated in metastatic melanoma cell lines and patient samples and this high expression correlates with a reduced overall survival of melanoma patients." (PMID 32719412, 2020). "The RAD51 response of melanoma cells to cisplatin could have been due to decreased synthesis, or increased proteolysis, possibly simply as a consequence of cisplatin-induced apoptosis." (PMID 29254481, 2017). "We conclude that the novel RAD51 transcriptional response to cisplatin in melanoma cells results in improved survival and growth over the time course of our assay compared to melanoma cells also expressing near endogenous levels of RAD51, but under ectopic promoter control." (PMID 29254481, 2017). "Since two such polymerases, DNA pol ζ (zeta) and DNA pol η (eta), have been implicated in cisplatin bypass, we decided to investigate whether the novel RAD51 response of melanoma to cisplatin also involved altered expression of these two TLS polymerases." (PMID 29254481, 2017). "We next began to consider how the unusual RAD51 response of melanoma cells to cisplatin might be connected to the resistance of melanoma to chemotherapy." (PMID 29254481, 2017).
melanoma (continued). "The unusual RAD51 response to cisplatin in melanoma cells led us to hypothesise that we could induce synthetic lethality and so render melanoma sensitive to PARP inhibitors by simultaneous exposure to cisplatin." (PMID 29254481, 2017). "Increased levels of ERCC1-XPF endonuclease activity could also facilitate increased repair of cisplatin-induced ICLs by HRR during S phase, but melanoma cells show strong transcriptional downregulation of the key HRR protein RAD51 in response to cisplatin?" (PMID 29254481, 2017). "The melanoma-specific effect of cisplatin on RAD51 expression could also be mediated by one or more of the same transcription factors." (PMID 29254481, 2017). "We next investigated whether increased proteolysis by either of the two main pathways was also contributing to the cisplatin-induced reduction in RAD51 levels in melanoma." (PMID 29254481, 2017). "In terms of HR, SAHA attenuates Rad51 upregulation in melanoma and rhabdomyosarcoma cells after IR." (PMID 24130769, 2013). "Inhibition of RAD51 led to the accumulation of DNA damage and enhanced drug efficacy in drug-naïve, vemurafenib-resistant and vemurafenib and trametinib double-resistant melanoma cells, as well as in a xenograft of melanoma cells isolated from a patient with developed resistance to vemurafenib." (PMID 33800547, 2021). "Therefore, we focused on Rad51 expression and confirmed that also Rad51 protein was strongly expressed in most human melanoma cell lines, in contrast to primary human melanocytes (FM) and primary human fibroblasts (FF), which have either no or very low levels of Rad51." (PMID 32719412, 2020). "On the functional level, the Elk1 knockdown increased the sensitivity of melanoma cells to the two Rad51i used, B02 and RI-1, most likely due to the double reduction of Rad51 function, on the one hand by Rad51i and on the other hand by the Rad51 deregulation mediated by Elk1." (PMID 32719412, 2020). "We show that Rad51 may be a promising new target for the treatment of melanoma." (PMID 32719412, 2020). "For instance, entinostat, a class I histone deacetylase (HDAC) inhibitor, reduced the expression of RAD51 and FANCD2, which, in turn, sensitized melanoma cells to TMZ and allowed for synthetic lethal targeting of PARP with olaparib." (PMID 33800547, 2021). "The healthy fibroblasts SBLF7 and SBLF9 as well as the melanoma cell lines ANST and LIWE were HR-proficient, which was indicated by an increase of the RAD51 foci." (PMID 34073147, 2021). "Enhanced lethality in PTEN-null melanoma tumors has been reported following PARP, RAD51 and ATR inhibition." (PMID 33800547, 2021). "The combined inhibition of the MAPK pathway and Rad51 increased the effect on the viability of R, RR, and PDX melanoma cells compared to the effects of single agent treatments." (PMID 32719412, 2020). "We show that the expression of RAD51 and other HRR genes is regulated by the MAPK-Elk1 signaling axis in melanoma cells." (PMID 32719412, 2020). "We have shown an overexpression of RAD51 and other HRR genes, DDB2, XRCC2, BRCA1 and BRCA2, in melanoma cell lines and this has a protective role against DNA damage accumulation after genotoxic stress." (PMID 32719412, 2020). "In concordance, inhibition of histone deacetylases class I resulted in suppression of HR due to down-regulation of RAD51 and FANCD2 and sensitized malignant melanoma cells to a synthetic lethal effect of olaparib combined with alkylating drug temozolomide." (PMID 27705909, 2016). "RAD51 staining showed that healthy fibroblasts raise the number of RAD51 foci after blocking the NHEJ-related protein DNA-PK, assuming a proficient HR pathway, as well as in the BRAF wildtype melanoma cell line LIWE." (PMID 36229655, 2023).